SOCS3 (suppressor of cytokine signaling 3)
Diseases named in the same sentence as SOCS3 in open-access papers (continued):
Sharing a sentence is not in itself a finding about the gene and the disease.
iron deficiency (1 paper, 2026). "By calibrating hepcidin through SOCS3-, FGL1-, and HIF2α-mediated control of IL-6-STAT3 and BMP-SMAD, RYGB mitigates the risk of profound iron deficiency while preserving beneficial macrophage and metabolic adaptations." (PMID 41598416, 2026).
ischemia reperfusion injury (1 paper, 2021). Adverse functional, metabolic, or structural changes in ischemic tissues resulting from the restoration of blood flow to the tissue (reperfusion), including swelling; hemorrhage; necrosis; and damage from free radicals. "Our present results suggest that myocardial SOCS3 is a potent inhibitor of IPC-induced cardioprotection, and that myocardial SOCS3 inhibition augment IPC-mediated cardioprotection during ischemia reperfusion injury." (PMID 34292971, 2021).
ischemic stroke (1 paper, 2021). A stroke disorder caused by obstruction of blood flow to the brain, due to thrombotic (local blood clot formation) or embolic (due to a blood clot or other material traveling from another site) event. "SOCS3 displayed a tremendous increase in all four target genes following ischemic stroke." (PMID 35008586, 2021).
joint diseases (1 paper, 2013). "Thus, they propose that SOCS3 could play a central role in the pathophysiology of joint diseases by deregulating chondrocyte function." (PMID 23638389, 2013).
Kawasaki disease (1 paper, 2026). A rare inflammatory disease characterized by an acute febrile, systemic, self-limiting, medium-vessel vasculitis primarily affecting children. "Five biomarkers-CD177, Matrix Metallopeptidase 9, Nuclear Factor Erythroid 2, Colony Stimulating Factor 3 Receptor, and Suppressor Of Cytokine Signaling 3-were consistently upregulated in Kawasaki disease and showed high diagnostic accuracy (area under the curve >0.94 in both datasets)." (PMID 41743406, 2026).
kidney failure (1 paper, 2021). An acute or chronic condition that is characterized by the inability of the kidneys to adequately filter the blood. "Loss of SOCS3 in the adult endothelium leads to severe vasculopathy and kidney failure under systemic inflammation that is associated with an increased type I IFN–like transcriptional program." (PMID 34138760, 2021). "Deletion of SOCS3 from the endothelium induced a much more severe response, suggesting complete kidney failure, as seen by the fact that there was no clearance of FITC-sinistrin within the 90-minute period of this assay." (PMID 34138760, 2021).
knee osteoarthritis (1 paper, 2023). "In contrast, compression-only stimulation, a physical stimulus that can be present at sites of knee osteoarthritis where the ECM has degenerated, was found to increase Socs3 expression." (PMID 37630168, 2023).
large cell medulloblastoma (1 paper, 2016). A medulloblastoma composed of large cells with prominent nucleoli and a larger amount of cytoplasm in contrast with the cells of the classic medulloblastoma. "Statistical correlations were established between p-STAT3 nuclear translocation and the level of SOCS3 (R = 0.333; p = 0.047) or PIAS3 expression (R = −0.494; p = 0.002) but not p-SHP2 down-regulation (R = 0.02; p > 0.05) in the large-cell medulloblastomas." (PMID 28035977, 2016).
leishmaniasis (1 paper, 2024). Infectious disease that is transmitted through the bite of hematophagous female phlebotomine sand flies. "The identification of hub genes of recruited datasets suggested that TNF, SOCS3, JUN, TNFAIP3, and CXCL9 may serve as potential infection biomarkers and could deserve value as prognostic biomarkers for leishmaniasis." (PMID 38839916, 2024).
lupus nephritis (1 paper, 2025). Glomerulonephritis in the context of systemic lupus erythematosus. "These inconsistencies underscore the complexity of SOCS3’s role in lupus nephritis and highlight the necessity for further investigation to elucidate its dual effects across different disease contexts and cell types." (PMID 40755762, 2025).
malaria (1 paper, 2019). Malaria is a serious and sometimes fatal disease caused by a parasite that commonly infects a certain type of mosquito which feeds on humans. "Remarkably, immunoregulatory molecules like SOCS1 and SOCS3 were found altered in each malaria sub-groups by the fold change value of 4.04 and 1.88 in UC1 while 4.55 and 3.12 in severe case group, respectively, compared to endemic control." (PMID 31614626, 2019).
metastatic colorectal cancer (1 paper, 2015). "Mutational analysis of the gene revealed no marked association between SOCS3 promoter region polymorphisms and the risk of developing metastatic colorectal cancer." (PMID 26482433, 2015).
metastatic melanoma (1 paper, 2010). A melanoma that has spread from its primary site to another anatomic site. "The baseline expression of SOCS1 and SOCS3 protein was measured in a panel of n = 10 human metastatic melanoma cell lines by immunoblot analysis." (PMID 20398276, 2010).
mycosis fungoides (1 paper, 2023). Classical mycosis fungoides is the most common type of mycosis fungoides (MF), a form of cutaneous T-cell lymphoma, and is characterized by slow progression from patches to more infiltrated plaques and eventually to tumors. "The study aimed to assess the expression of suppressor of cytokine signaling-3 (SOCS-3) in patients’ skin with mycosis fungoides to evaluate the possible role of SOCS-3 expression in the pathogenesis of mycosis fungoides." (PMID 35226171, 2023). "This study aimed to assess the expression of SOCS-3 in patients’ skin with mycosis fungoides to elucidate their possible role in the pathogenesis in MF." (PMID 35226171, 2023). "Increased tissue levels of SOCS-3 patients with mycosis fungoides point to a role that SOCS-3 could play in its pathogenesis." (PMID 35226171, 2023).
myeloid leukemia (1 paper, 2016). A clonal proliferation of myeloid cells and their precursors in the bone marrow, peripheral blood, and spleen. "SOCS3 has been shown to be silenced in solid tumors as well as myeloid leukemia; however little is known about the regulation in CLL." (PMID 27107422, 2016).
Neonatal sepsis (1 paper, 2020). Systemic inflammatory response to infection in newborn babies. "The role of SOCS1 and SOCS3 for immunomodulation during neonatal sepsis warrants further investigation." (PMID 32479514, 2020). "Although the direct mechanisms of the SOCS family of proteins have not been established for neonatal sepsis, our findings suggest a potential role for SOCS1 and SOCS3 in dampening interferon responses." (PMID 32479514, 2020).
nodular medulloblastomas (1 paper, 2016). "The frequencies of SOCS3 cytoplasmic detection were 100% (17/17) in the tumor-surrounding brain tissues, 80.3% (49/61) in the classical, 90.9% (40/44) in the large-cell and 80.0% (12/15) in the nodular medulloblastomas." (PMID 28035977, 2016).
non-Hodgkin lymphoma (1 paper, 2021). Distinct from Hodgkin lymphoma both morphologically and biologically, non-Hodgkin lymphoma (NHL) is characterized by the absence of Reed-Sternberg cells, can occur at any age, and usually presents as a localized or generalized lymphadenopathy associated with fever and weight loss. "Indeed overexpression of SOCS3 in the peripheral blood of non-Hodgkin lymphoma (NHL) patients correlated with advanced disease and a poor response to treatment." (PMID 34604264, 2021).
pancreatitis (1 paper, 2024). Inflammation of the pancreas. "Clarification of the role of SOCS3 and TLR4 in macrophage polarization is also of interest in the progression of pancreatitis as deletion of SOCS3 resulted in more beneficial outcomes following induction of pancreatitis." (PMID 38585277, 2024). "The role of SOCS3 in the activation of macrophages in pancreatitis is further supported by a study showing that macrophage-specific deletion of SOCS3 developed less severe pancreatitis and produced less TNFα in response to cerulein injections." (PMID 38585277, 2024).
parasitic infection (1 paper, 2022). "The probiotic treatment significantly increased mRNA expression of genes associated with enhanced protection against parasitic infection, including IL-25, RETNLB, and SOCS3, and did not interfere with the normal expulsion of L4 from the jejunum." (PMID 35335620, 2022).
plasma cell leukemia (1 paper, 2017). An aggressive plasma cell neoplasm characterized by the presence of neoplastic plasma cells in the peripheral blood. "Moreover, association of SOCS3 methylation with plasma cell leukemia, elevated LDH, and shortened survival (6.9 versus 56.1 months) was observed." (PMID 28404963, 2017).
prion disease (1 paper, 2020). A transmissible disease that is caused by a protein that is able to induce abnormal folding of normal cellular proteins, leading to characteristic spongiform brain changes, which are associated with neuronal loss without an inflammatory response. "SOCS3 was one of the few identified genes that were suggested to be prion disease pathogenesis-specific." (PMID 33375642, 2020).
prostate adenocarcinoma (1 paper, 2022). "To assess the translational impact of SOCS3 regulation by IL30 expression in human PC cells, we analyzed RNA-Seq data of tumor samples from 494 PC patients, included the “Prostate Adenocarcinoma TCGA PanCancer” collection, along with their clinicopathological profiles." (PMID 36224639, 2022). "The clinical relevance of our experimental findings is substantiated by the Kaplan–Meier curves of PC patients, from the “Prostate Adenocarcinoma TCGA PanCancer” collection, which show a shorter PFS for patients diagnosed with IL30 mRNAHigh tumor and patients with SOCS3 mRNALow tumor." (PMID 36224639, 2022).
pyrexia (1 paper, 2019). "This is in correlation with our findings that pyrexia induces SOCS-3 expression, resulting in increased cleavage of caspase-3, which could be temporarily attenuated by hypothermia." (PMID 31871429, 2019).
retinal degeneration (1 paper, 2025). Degeneration of the retina. "In summary, our findings in preclinical models of inherited retinal degeneration show that antagonizing the cytokine signaling inhibitor SOCS3 can potentiate endogenous neuroprotective capacities and effectively prolong neuron survival without compromising visual function." (PMID 40671803, 2025).
rosacea (1 paper, 2021). A chronic erythematous skin disorder that affects the face. "Through rosacea histopathological analysis, we found that the expression of SOCS3 in the rosacea lesion area was significantly higher than that in the surrounding area." (PMID 33545988, 2021). "It is speculated that this might be due to the increase in multiple inflammatory factors in the rosacea lesions and the feedback-mediated promotion of the expression of the anti-inflammatory factor SOCS3." (PMID 33545988, 2021). "Our study further verified that there is high macrophage infiltration into rosacea lesions, as well as enhanced expression of the inflammatory factors LL37, IL-1β, and SOCS3." (PMID 33545988, 2021). "PF promoted SOCS3 expression in RAW 264.7 cells and inhibited the LPS-induced increase in toll-like receptor 2 and LL37 expression through the ASK1-p38 cascade, thereby alleviating the macrophage-related rosacea-like inflammatory response." (PMID 33545988, 2021).
Rotavirus infection (1 paper, 2024). Infection with any of the rotaviruses. "Our results indicated that, in HT-29 cells with both microorganisms before rotavirus infection, the relative expression of SOCS3, IFN-γ, STAT1, and IL-10 was significantly (p < 0.05) upregulated." (PMID 38791551, 2024).
sarcoidosis (1 paper, 2022). Sarcoidosis is a multisystemic disorder of unknown cause characterized by the formation of immune granulomas in involved organs. "HBEGF interacts with SOCS3, a suppressor of cytokine signaling with an ability to inhibit Jak/STAT signaling, with elevated expression in lymph nodes sarcoidosis, we previously identified dysregulated HBEGF gene expression in PBMCs sarcoidosis." (PMID 36388923, 2022).
Schistosoma haematobium infection (1 paper, 2008). "Presence of Schistosoma haematobium infection, reported to decrease the risk of atopy and observed in the current study, affected the expression levels of TLR2 and SOCS-3, which were significantly lower in infected children." (PMID 18414649, 2008).
silicosis (1 paper, 2024). Silicosis is a respiratory disease caused by breathing in (inhaling) silica dust. "Our findings clearly support the theory that BIC reduces inflammation in silicosis via inhibitory effects on the JAK2/STAT3/SOCS3 signaling pathway." (PMID 39060930, 2024). "Consistently, abnormally activated JAK2 and STAT3 as well as aberrantly expressed SOCS3 in lung tissues of silicosis rats were downregulated by BIC in the silicosis model." (PMID 39060930, 2024).
sporotrichosis (1 paper, 2024). The commonest and least serious of the deep mycoses, characterized by nodular lesions of the cutaneous and subcutaneous tissues. "Here we found SOCS3 was also upregulated, suggesting that the mechanism of the JAK/STAT pathway in sporotrichosis is complex." (PMID 38172590, 2024). "The results showed that the protein expressions of IL-6, JAK3, STAT3, and SOCS3, as well as phosphorylated JAK3 and STAT3, were significantly upregulated, suggesting that the JAK/STAT signaling pathway was activated during the occurrence and development of sporotrichosis." (PMID 38172590, 2024).
Streptococcus pneumonia (1 paper, 2023). "In neutrophils treated with VitD3 and infected with Streptococcus pneumonia, there is increased expression of SOCS-1 and SOCS-3 compared to non-treated neutrophils." (PMID 35850625, 2023).
T-LGL leukemia (1 paper, 2022). "The finding of an miR-181a-SOCS3-pSTAT3 axis in T-LGL leukemia is of broader importance, as it could potentially clarify why STAT3 nonmutated patients also acquire hyper-activation of the STAT3 molecule." (PMID 34873301, 2022). "Even though this might seem counter-intuitive given that in other cell contexts SOCS3 expression is induced by pSTAT3 activation, this is in line with earlier literature on SOCS3 expression in T-LGL leukemia." (PMID 34873301, 2022). "We identified that the overexpression of one particular miRNA, miR-181a, which results in hyperactive STAT3 and ERK1/2 by decreasing SOCS3 and DUSP6 expression in T-LGL leukemia patient cells, eventually leads to resistance to FAS-mediated apoptosis." (PMID 34873301, 2022). "By using TL1, a human T-LGL cell line, we could show that miR-181a is an actor in T-LGL leukemia, driving STAT3 activation by SOCS3 inhibition and ERK1/2 phosphorylation by DUSP6 inhibition and verified this mechanism in an independent cell line." (PMID 34873301, 2022). "Notably, the STAT3 pathway is dysregulated as well, in particular through the inhibition of SOCS3, a protein that is absent in all T-LGL leukemia cells." (PMID 34873301, 2022).
takotsubo cardiomyopathy (1 paper, 2018). "As with our experimental model, there was a greater proportion of M1 macrophages (CD68/HLADR or CD68/SOCS3 positive) in myocardial tissue from takotsubo cardiomyopathy patients when compared with control tissue, again reflecting a potential proinflammatory response." (PMID 30623136, 2018).
Thrombocytopenia (1 paper, 2012). A reduction in the number of circulating thrombocytes. "Patients treated with pegIFNα 2a had significantly higher risk of thrombocytopenia, and carriers of the SOCS3 rs4969170 AA genotype had significantly lower risk of thrombocytopenia." (PMID 23133602, 2012). "Regarding thrombocytopenia, the model included the type of pegIFNα prescribed, stratified CD4 cell count, and SOCS3 rs4969170 genotype." (PMID 23133602, 2012).
urticaria (1 paper, 2025). A vascular reaction of the skin characterized by erythema and wheal formation due to localized increase of vascular permeability. "S100A7, S100A8, S100A9, S100A12, IL6 and SOCS3, whose mRNA expression correlated positively with the urticaria activity score and may have a potential diagnostic value." (PMID 40635160, 2025).
varicella (1 paper, 2016). "Varicella zoster virus that causes varicella (chickenpox) and herpes zoster (shingles) induces increased levels of SOCS3." (PMID 27367734, 2016).